IRF7 (interferon regulatory factor 7)
Diseases named in the same sentence as IRF7 in open-access papers (continued):
Sharing a sentence is not in itself a finding about the gene and the disease.
infection (continued). "Moreover, similar expression levels for several Interferon-stimulated genes (ISGs), namely Ifit1, Ifi44, Usp18, Ifit3 and Irf7, were observed in the livers of Ctrl and RKV-supplemented mice at various time points after infection." (PMID 33294789, 2020). "Furthermore, carvedilol increased the phosphorylation of TBK1, IRF3, IRF7, and STING and the dimerization and translocation of IRF3 after the infection." (PMID 33243993, 2020). "Whereas vehicle-inoculated mice did not express HMGB1 in the ASM, its expression increased incrementally over the course of infection in the ASM bundles of IRF7-/- but not WT mice, similar to the pattern of ASM growth." (PMID 32658914, 2020). "Further characterization revealed that Irf3−/− mice, but not Irf7−/− mice, showed a similar early increase in liver parasite burden as Ifnar1−/− mice following P. yoelii (Py17XNL) infection." (PMID 33408718, 2020). "In contrast to susceptible Irf-7−/− mice, wildtype mice showed no disease signs upon LGTV infection." (PMID 32951602, 2020). "Infection of specific pathogen-free chickens with Newcastle Disease Virus was followed by increased expression of STING together with that of interferon (INF)-α, INF-β, and Interferon Regulatory Factor 7 (IRF-7) in the spleen." (PMID 33240094, 2020). "Knockout experiments in mice have shown that lack of IRF3 delays the immune response, while cells lacking IRF7 respond early but are unable to fend off the infection without the signal amplification." (PMID 32645843, 2020). "M. avium infection induced IRF3 and IRF7 nuclear translocation in WT but not Mavs–/–BMMs at 24 hr post-infection." (PMID 32463840, 2020). "Similarly, Irf7−/− mice infected with CHIKV developed worse clinical disease (foot swelling) and sustained high viral loads at the site of infection and sites of dissemination." (PMID 33408718, 2020). "In contrast, the infection had no dramatic impact on the activation status of the astrocytes in Irf-7−/− mice." (PMID 32951602, 2020). "Probing the lung tissue for TGF-β expression by immunohistochemistry revealed the airway epithelium and ASM (clearly evident by morphology) to be a rich source of TGF-β following infection, and that its expression in ASM cells was significantly greater in IRF7-/- mice compared to WT mice." (PMID 32658914, 2020). "This is consistent with the differences in the transcriptional profiles found between PM-MQC and FPKC after infection with rNJ0612NME6 and M51R, where the transcriptional profile of IRF-7 and IFN α in FPKC was not different between the two viruses." (PMID 32587580, 2020). "Following infection, the genes CASP6 and IRF7 were upregulated by greater than twofold." (PMID 31462004, 2019). "While STING was originally shown to activate not only IRF3 but also IRF7 and IRF3 and IRF7 have been shown to have non-redundant roles in different infection models, IRF3 is generally described in reviews as the main IRF downstream of cGAS and STING." (PMID 31877196, 2019). "IRF7 is an essential factor in the amplification of IFN-I production, and IRF7 but not IRF3 is required for the induction of IFN-Is following IP infection with LCMV-Arm." (PMID 30791575, 2019). "In contrast to the engineered type I IFN response in iPSCs through overexpression of IRF7, no morphological changes were noted after infection of iPSCs with RV." (PMID 31405163, 2019). "Infection with the CHa strain induced significantly increased expression of cGAS, RIG-I, MDA5, IRF7, IFN-β, and MX in monocytes/macrophages at 6 hpi, and these levels were higher than those observed in mock-treated cells but lower than those in cells infected with CHv strain." (PMID 32063900, 2019). "Furthermore, interaction analysis of IRF7 overexpression and H6N2 infection was performed to discover the genes that were differentially regulated during the infection due to IRF7 overexpression." (PMID 30356848, 2018).
infection (continued). "By contrast, pDC:Irf7+ mice experienced no overt clinical symptoms with 100% of mice surviving infection." (PMID 29914621, 2018). "In addition, we analyzed the transcriptome of IRF7 overexpression and control cells by RNA-seq after LPAIV or mock infection to examine candidate genes and pathways that are potentially modulated by IRF7 upon AIV infection." (PMID 30356848, 2018). "RRV-T48A534V infection results in upregulation of RIG-I, MyD88, and IRF7 expression." (PMID 30131356, 2018). "Consistent with previous in vivo data, IOE infection enhanced expression of IRF7 and IFNβ in WT-BMM, but not in MyD88-/- BMM." (PMID 29049365, 2017). "Thus, IFN-independent signaling should participate in the upregulation of PKR, especially during early infection (12 h p.i.)when PKR was statistically induced in contrast to IFN, IRF1, and IRF7." (PMID 29069722, 2017). "Although mild hunching was observed for 1 to 2 days after ZIKVMR766 infection, no IRF7−/− mice required euthanasia after s.c. infection with either virus at 3 log10 CCID50." (PMID 28529976, 2017). "Given that Ly6Chi monocytes express type I IFN in an IRF3/IRF7-dependent manner in response to co-culture with RRV-infected cells, we next assessed whether monocytes express Irf7 and/or type I IFN during infection in vivo." (PMID 29244871, 2017). "To further investigate downstream mechanisms of inhibition of the IFN-α/β response by ROCV prM-E proteins, we used IRF3−/− × IRF7−/− MEF cells, which lack the ability to produce IFN-α/β in response to infection, but maintain the ability to respond to exogenous IFN-α/β." (PMID 28317911, 2017). "Cellular infiltrate was quantified over the course of infection, which showed a significant increase in total cells resident in the lungs on day 7 postinfection in IRF7−/− mice but not in IRF1−/− mice (P < 0.05)." (PMID 27822537, 2016). "First, the gene expression studies were conducted at a single time point post infection (24 h), so it was not possible to determine the role of IRF7 in the kinetics of the response." (PMID 26810609, 2016). "Components of interferon pathway and innate immunity (IFI44L, IFITM3, MX1, IRF7, OAS2, STAT2, etc.)are significantly upregulated in the acute phase of infection, while the expression levels of genes involved in translational elongation and protein biosynthesis are decreased." (PMID 26070066, 2015). "We therefore examined gene expression for several important interferon-related genes (IFNα2, IFNα4, IFNβ, IFNαβR, IFNγ, IFNγR, Irf3, Irf7, Mx1, Oas1, IFITM1, IFITM2), along with inflammasome-related genes IL-1β and NLRP3, and chemokines CCL5, CCL7, and CCL12 at d1 post-infection." (PMID 26110868, 2015). "Since IRF-3 stimulates IFN-β production and IRF-7 induces both IFN-α and IFN-β production, the significance of IRFs in each infection model could possibly hint on the importance of IFN-α and/or IFN-β at different window of the liver-stage infection." (PMID 25157202, 2014). "Pretreatment of cells did not prevent subsequent infection with Neospora (not shown), but blocked Neospora induction of the antiviral genes IRF7 and HERC5, 3-fold and 4-fold, respectively." (PMID 24505488, 2014). "By 24 h of infection, however, expression of all four anti-viral genes and IFN-β and IL-6 was clearly up-regulated (p<0.05) in all three cell types; BEAS-2B cells displayed the highest expression of IRF-7, STING, Mx1 and IL-6." (PMID 25313647, 2014). "We immunized Irf7−/− rather than wild type (WT) mice, as CHIKV replicated to higher titers, induced stronger neutralizing antibody responses, yet did not cause lethal infection in these innate immune-deficient animals (, and data not shown)." (PMID 23637602, 2013).
infection (continued). "To determine whether IRF-3 was responsible for synthesis of type I IFN during Y. pestis infection, we challenged wild type, Irf3−/− and Irf7−/− mice with Y. pestis KIM D27 and measured gene expression in the lungs on days 2 and 4 post-infection." (PMID 22911267, 2012). "The linkage between TLR7 and LMP1 expression is intriguing: primary infection of B lymphocytes by EBV may induce the expression of TLR7, IRF5, and IRF7." (PMID 22952664, 2012). "While it appeared that Ifnβ expression was decreased in Irf3−/− and Irf7−/− mice compared to wild type on day 4 post-infection, expression of this cytokine was not fully dependent on either transcription factor." (PMID 22911267, 2012). "Similar to IFNβ mRNA induction, IRF7, Mx1 and ISG15 mRNA levels could also be detected as early as 3 hrs post-infection, with peak levels observed at 16 hrs post-infection." (PMID 22028657, 2011). "For example, RAW264.7 cells, a commonly used cell line in the study of Leishmania-macrophage interactions, responds minimally to infection with IRF-7 induction, and hence this pathway would not be evident in studies using this host-pathogen combination." (PMID 20300600, 2010). "NF-κB and IRF7 transcript levels, which are both MYD88 and TRIF dependent, were significantly increased after ΔTcpC infection compared to CFT073 (p<0.01), suggesting that also TRIF-dependent signaling, might be inhibited by TcpC." (PMID 20886104, 2010). "Though NFkB, IRF7 and IRF3 silencing decreased ISG15 expression, only IRF7 decreased the level of the reporter gene expression by more than 50% and partially reverted the resistance to infection with Ad5GFP." (PMID 20113473, 2010). "As expected, transfection of IRF7 alone without VP35-HA enhanced IFNβ promoter activity even before infection, and NDV infection increased reporter activity by about two-fold." (PMID 19557165, 2009). "Both IRF3 and IRF7 were upregulated in lungs, but not nose, with infection." (PMID 40956633, 2025). "In our analysis, we did not detect IRF3 in both LmWT and LmCen–/– infections indicating that IRF7 alone may be sufficient to induce the type-I response following Leishmania infection." (PMID 39702382, 2024). "The results showed that the expression of MAVS, IRF7, STING, NF-κB, MAD5, LGP2, IFN-α and IFN-β was upregulated compared with that in the control group, regardless of whether IFITM3 was overexpressed or inhibited after infection." (PMID 38543696, 2024). "Additionally, this study provided only a preliminary exploration of upstream factors affecting IFNα and IP10, necessitating further clinical data and animal experiments to reveal the regulatory roles of IRF5, IRF7, and IFNAR in severe E11 infection in neonates." (PMID 39045132, 2024). "IEIs of TLR3-, IRF7-, UNC93B1-, TICAM1-, TBK1-, and interferon alpha and beta receptor subunit 1 (IFNAR1)-dependent type I interferon immunity have been described to underlie life-threatening COVID-19 pneumonia in patients with no prior severe infection." (PMID 37559153, 2023). "In contrast, Irf7−/− mice showed no increase of serum IFN-I levels upon infection." (PMID 37737190, 2023). "Finally, the expression of irf7 at 48, 72, and 96 h after infection reached the level similar to that at 6 h without infection; however, the expression of irf7 at 96 h without infection was also promoted." (PMID 36059498, 2022). "Overexpression of IRF7 in KO IFNAR1 cells infected with DTMUV partially restored the expression of IFN-β at 12–48 hpi, IFIT5 at 36–48 hpi, IRF1 at 48 hpi, and MX1 at 12–48 hpi, indicating a type I IFN-independent role of IRF7 in the induction of these genes during DTMUV infection." (PMID 35891486, 2022). "PLAAT1 colocalized with IRF3 and IRF7 without or with SVCV infection." (PMID 36172355, 2022).
infection (continued). "In our study, we observed that treatment with BCP-DHA, regardless of the presence of infection, negatively regulated the gene expression of IL-2, IL-6, IRF7, NLRP3, and TYK2, acting directly in NF-ĸB inhibition and the synthesis and activity of pro-inflammatory cytokines." (PMID 36357780, 2022). "This infection-induced MHC class I expression was not present in IRF7 ∆DBD cells." (PMID 34389779, 2021). "Furthermore, while IFNAR2 blockade (which repressed the IFNβ-IRF7 forward feedback loop) did not affect the expression pattern in the high MOI infection, it significantly repressed all subtypes except IFNα1, -α2, and -α8 after low MOI infection." (PMID 33542718, 2020). "Cell adhesion molecules, particularly integrins, play important roles as mediators in surveillance and the regulation of immune cell functions, and we observed the up-regulation of integrins as a result of altered IRF7 expressions in any direction, even in the absence of infection." (PMID 32252379, 2020). "Of the interferon regulatory factor (IRF) genes annotated in KEGG, expression of IRF7 was significantly upregulated, and interestingly, all downstream transcriptional targets of IRF9 annotated in KEGG (MX1, OAS genes, ADAR, and PML) were consistently upregulated during acute infection." (PMID 30150281, 2018). "We believe that although Csn-B may activate both IRF3 and IRF7, it might activate signaling events that lead to the phosphorylation of IRF3 more efficiently than IRF7, a process that may contribute to counter IAV in the early stages of infection." (PMID 29053748, 2017). "Notably, the IFN-β and IRF-7 were up-regulated earlier at day 4 after HEP-Flury infection but not in CVS-11 infection, and IFN-γ was significantly elevated in the HEP-Flury infected mouse brains than the CVS-11 infected mouse brains after 10 dpi." (PMID 27242764, 2016). "Notably, although NcoR2 and HDAC3 remained at a high level over the infection period, they failed to reside on IRF7 promoter and hinder its transcription when Bcl6 expression was suppressed by miR-127." (PMID 26728228, 2016). "Thus, to address a potential redundancy among IRF family members in modulating HIV-1 expression, in a critical proof of concept experiment we found that decreasing IRF7 transcription resulted in 7- and 120-fold increase in HIV-1 transcription on days 1 and 3 after infection." (PMID 26121689, 2015). "However, two immune-regulatory genes (IRF7 and KHSRP) were not responsive to highly pathogenic H5N1 infection but were strongly up-regulated in DF-1 cells infected with low pathogenic H9N2 infection." (PMID 25557928, 2015). "In contrast, there were no changes in the gene expression levels of IRF7 when IFN-β neutralizing antibody was added to the cells early during infection; which is indicative of IRF7 playing little to no role in the synthesis of IFN-β early during C. muridarum infection." (PMID 25798928, 2015). "We were not able to observe an obvious peak of phospho-IRF7 at 6 h post-infection." (PMID 24722640, 2014). "However, upon infection with SE, we found 11 of the TLR reference genes that were significantly up-regulated in heterophils from line A when compared to line B (MD-2, TIRAP, IRAK4, TRAF3, TAK1, IKKε, IKKα, NF-κB2, PI-3K, p38, and IRF7)." (PMID 22783275, 2012). "It is likely that Heat-VAC infection of pDCs produces long, uncapped and partially double-stranded viral RNA transcripts that are sensed by the endosomal RNA sensor TLR7, which utilizes its adaptor MyD88 to activate transcription factor IRF7, resulting in the induction of type I IFN." (PMID 22606294, 2012). "Hence it was not surprising that IRF-7 was also one of the genes significantly elevated following infection with the ORF45 null recombinant virus in our present study." (PMID 20485504, 2010). "However, in contrast to B6 mice, B6.Irf-7−/− mice failed to eliminate intracellular amastigotes over the first 24h of infection." (PMID 20300600, 2010).
infection (continued). "RTA-dependent ubiquitylation of interferon regulatory factor 7 (IRF7), a key inducer of interferon-stimulated genes (ISGs), could target it for ubiquitin-dependent proteasomal degradation, thus dampening innate immune responses to the infection." (PMID 18047745, 2007). "However, systemic review of IRF7 in inflammation, cancer and infection is still lacking." (PMID 37251373, 2023). "In addition, the IRF-7 pathway was activated post infection with rDK212-ΔNS1, but not with DK212." (PMID 24939427, 2014). "However, upon infection with SE, we found a significant up-regulation in six other TLR signaling pathway genes in the heterophils from line A chickens: MD-2, TIRAP, IKKε, NF-κB2, p38 MAPK 11, and p38 MAPK 12 in addition to IRF7 when compared to line B heterophils (p < 0.01)." (PMID 22783275, 2012). "Cells with the IRF-7 shRNA sequences were not able to develop antiviral responses upon infection with ORF45-null mutant virus as compared to control cells (with no IRF-7 knockdown) in which infection with ORF45-null virus conferred cell resistance to VSV superinfection." (PMID 20485504, 2010). "Consistently, we found that IRF7 mRNA expression, but not IRF3 mRNA, was induced after 6 h of infection and was reduced by M3, further confirming that IRF7 activation is regulated by IFN." (PMID 39601535, 2025). "We repeated this analysis using the virus only conditions and found that IRF5, but not IRF3 or IRF7, was significantly upregulated in HIV-1–infected MDMs isolated from older donors despite similar levels of infection in vitro." (PMID 40493408, 2025). "In this study, we found that IRF7 and IFN-β expression were suppressed in DF-1 cells during infection with very virulent IBDV (vvIBDV), but not with attenuated IBDV, while the virus continued to replicate." (PMID 39872942, 2024). "The mRNA expression levels of IL-6, IL-18, IFN-α, IFN-β, and ISG-15 were up-regulated during EV-G/YN23/2022 infection, while IL-1β, TNF-α, IFN-λ3, and IRF-7 maintained in relatively constant levels, and no cytokines were significantly reduced." (PMID 37632087, 2023). "Here, we demonstrate that during infection with the neurotropic Langat virus (LGTV), an attenuated member of the tick-borne encephalitis virus (TBEV) subgroup, neurons do not rely on IRF7 for cell-intrinsic antiviral resistance and IFN-I induction." (PMID 37737190, 2023). "Gene expression analysis of the nasal tissue revealed that early infection (4 dpi) did not alter TLR expression, including that of TLR7 despite virus being present and evoking elevated IRF-7 and IFN-β expression." (PMID 37795093, 2023). "We found that the mRNA expression level of IRF7 was significantly increased at 18 and 24 h after SVA infection (P < 0.05), but the mRNA expression level of IRF3 was not significantly increased (P > 0.05)." (PMID 35308346, 2022). "In line with IFNRT, also KO of IRF9 again prevented the upregulation of IRF7 and also IRF2, but peculiarly, different from in the infection setting it did not lead to augmentation of IRF1 induction." (PMID 34685580, 2021). "Mavs-/- and Irf3-/-Irf7-/- mice, both of which lack the signaling downstream of RLRs required for virus-induced IFN synthesis, are just as permissive for infection as Ifnar1-/- mice, but they do not develop liver disease when infected with HAV." (PMID 34591933, 2021). "Together these studies demonstrate that while IRF7 is not essential for the IFN-I response to LCMV, it is required for the optimal early antiviral response to infection." (PMID 30791575, 2019). "On the other hand, the expression of TLR3, IRF-7, OASL1, and OASL2 in tumor cells 8 h post infection showed a significantly negative correlation with the rNDV infection rate." (PMID 29882780, 2018). "While IRF3 was partially implicated in S. suis-induced IFN-β by DCs, its expression was not modulated following infection with S. suis, unlike that of IRF1 and IRF7." (PMID 28894449, 2017).